MET (MET proto-oncogene, receptor tyrosine kinase)
Diseases named in the same sentence as MET in open-access papers (continued):
Sharing a sentence is not in itself a finding about the gene and the disease.
gastric cancer (continued). "To date, no drug targeting the HGF/MET pathway has been approved for gastric cancer treatment, but antibodies or tyrosine kinase inhibitors against MET are currently being investigated in clinical trials (see introduction)." (PMID 31557260, 2019). "The anti-HGF antibody rilotumumab did not improve the clinical outcome in MET-positive advanced gastric cancer or gastroesophageal junction (GEJ) cancer in a phase III study (RILOMET-1)." (PMID 31557260, 2019). "We previously reported that high levels of tyrosine kinase receptor (RTK) gene amplification of EGFR, HER2, FGFR2, or MET had protein overexpression and rarely showed other coexisting gene alterations using the next-generation sequencing (NGS) method for gastric cancer." (PMID 28852882, 2018). "Several monoclonal antibodies and small-molecule inhibitors of c-MET have been evaluated in clinical trials, however, most of the phase III trials of MET inhibitors showed negative results for gastric cancer." (PMID 30104497, 2018). "More and more c-MET inhibitors have been found to have antitumor activity in gastric cancer, but many drug studies have only stayed in nonclinical stage." (PMID 30360560, 2018). "In gastric cancer, both HGF and c-MET contribute and participate in oncogenic pathways." (PMID 30360560, 2018). "To clarify the clinical relevance, we suggest the investigation of afatinib as a potential treatment option for trastuzumab‐resistant gastric cancer patients without MET amplification, independent of HER2 activation." (PMID 29325228, 2018). "The highly selective c-MET small molecule inhibitor volitinib is capable of inhibiting proliferative activity of gastric cancer cells via avoiding phosphorylation of c-MET, and thus inhibiting the activation of c-MET signaling and downstream pathway (AKT and ERK)." (PMID 30360560, 2018). "Rather, MET overexpression, high pT stage, and a lack of lymphatic invasion in gastric cancers represented histopathological features that were predictive of PD-L1 positivity." (PMID 29137273, 2017). "Aberrant activation of c-MET/HGF signalling leads to increased tumour proliferation, invasiveness and angiogenesis, resulting in poor prognosis in various human cancers, including non-small-cell lung cancer (NSCLC) and gastric cancer." (PMID 28315949, 2017). "The observations suggest that autophagy inhibitors should not be used to enhance the effects of MET inhibitors in gastric cancer patients." (PMID 28881678, 2017). "Overall, our results demonstrate that autophagy inhibitors do not potentiate MET inhibitor-induced apoptosis in gastric cancer cells." (PMID 28881678, 2017). "Several studies with large cohorts correlated MET gene amplification with advanced tumor stage and poor prognosis in gastric cancer patients undergoing surgery with or without chemotherapy." (PMID 27013592, 2016). "Taken together, activation of HGF/MET pathway were strongly associated with the resistance to HER2 inhibitor and this mechanism were more frequently observed in HER2-positve gastric cancer patients compared with HER2 negative patients." (PMID 26716644, 2016). "MET gene amplification ranging from frequencies of 1-20% has been documented in a variety of human cancers, including liver metastases from colon carcinoma, non-small cell lung carcinomas with acquired resistance to EGFR inhibitors and gastric cancers." (PMID 26879245, 2016). "Higher expression levels of RTKs were detected in gastric cancer tissues compared with normal tissues, and some RTKs (e.g., EGFR, HER2, c-MET and vascular endothelial growth factor receptor) have been known to induce invasion, metastasis and EMT in gastric cancer." (PMID 27121055, 2016). "MET, ATM, FGFR2, and HER2 were profiled on gastric cancer biopsy samples." (PMID 26587992, 2015). "Although MET kinase is regarded as one of the most promising therapeutic targets in gastric cancer, there are still a considerable number of MET+ patients who do not respond to anti-MET agents." (PMID 26528757, 2015).
gastric cancer (continued). "Also, Crizotinib as a c-MET inhibitor showed an antitumor effect via inhibition of c-MET signaling in lung and gastric cancer cells." (PMID 25193856, 2014). "To test whether other MET-amplified human cancer cells show a similar drug response pattern, we extended our experiments to MET-amplified H1993 and H1648 NSCLC cell lines and GTL-16 gastric cancer cells." (PMID 25551293, 2014). "Overexpression and amplification of MET occurs in many gastric cancers and one study has shown PHA-665752 as a potential target for MET amplification and Onartuzumab, a humanized anti-MET antibody, has been shown to produce sustained responses against MET copy number mutations." (PMID 25025766, 2014). "There are many novel compounds available today targeting different molecular pathways of gastric cancer such as HER2, EGFR, MET, FGFR, and PI3K/MTOR, which could potentially be used for the treatment of gastric adenocarcinomas." (PMID 25025766, 2014). "We examined the biological impact of MET amplification in gastric cancer cells by comparing the effects of the MET-TKIs JNJ38877605 and SGX523 between gastric cancer cell lines positive for MET amplification and those negative for this genetic alteration." (PMID 23327903, 2013). "Such transfection inhibited MET signal transduction as well as induced apoptosis in gastric cancer cell lines with MET amplification but not in those without it (data not shown)." (PMID 23327903, 2013). "The effects of MET tyrosine kinase inhibitors (MET-TKIs) in gastric cancer cells with or without MET amplification were also examined." (PMID 23327903, 2013). "MET amplification was assessed by initial screening with a PCR-based copy number assay followed by confirmatory FISH analysis in formalin-fixed, paraffin-embedded specimens of gastric cancer obtained at surgery." (PMID 23327903, 2013). "Inhibition of MET by MET-TKIs resulted in the induction of apoptosis accompanied by attenuation of downstream MET signaling in gastric cancer cell lines with MET amplification but not in those without this genetic change." (PMID 23327903, 2013). "Moreover, SRC rs6124914, c-MET rs41739 and CRK rs7208768 showed significant gene-dose effects for gastric cancer in both analyses." (PMID 22383989, 2012). "Though additional stratified analyses were also conducted to detect an interaction between CagA seropositivity and each gene effect for gastric cancer risk, interactions were not significant in any of the three genes, SRC, c-MET and CRK (data not shown)." (PMID 22383989, 2012). "We have therefore now investigated whether activation of MET contributes to STAT3 activation and further examined the roles of STAT3 in human gastric cancer cell lines." (PMID 21730976, 2011). "On the other hand, we found that gastric cancer cells in which STAT3 is activated in the absence of MET activation secreted IL-6, and this cytokine then activated STAT3 through the JAK pathway." (PMID 21730976, 2011). "In conclusion, we have shown that gastric cancer cell lines can be classified on the basis of the mechanism of STAT3 activation (induced by MET or IL-6) into distinct and non-overlapping subsets." (PMID 21730976, 2011). "This study evidences previously observed perturbations of the KRAS, ERBB2, EGFR, MET, PIK3CA, FGFR2 and AURKA genes in gastric cancer and suggests some of the targeted therapies approved or in clinical development would be of benefit to 11 of the 50 patients studied." (PMID 21781349, 2011). "Similar to the effects of PHA-665752, transfection with a siRNA specific for MET mRNA resulted in inhibition of STAT3 phosphorylation in gastric cancer cells with MET activation but not in MKN1 or MKN7 cells." (PMID 21730976, 2011). "Additionally, cabozantinib, an oral TKI targeting MET, VEGFR2, and Axl, is being studied in combination with the anti-PD-L1 agent durvalumab in advanced gastroesophageal cancers, including gastric cancer, in a phase I/II open-label multi-cohort trial (NCT03539822)." (PMID 41011010, 2025).
gastric cancer (continued). "This development of MET CAR-T represents an innovative approach for treating various solid tumors, exhibiting significant anti-tumor activity in papillary renal cell carcinoma (PRCC), recurrent nasopharyngeal carcinoma (rNPC), Ewing sarcoma (EWS), and gastric cancer (GC)." (PMID 39201787, 2024). "In gastric cancer, however, a MET IHC H-score of 150 had a 75% sensitivity and 78% specificity to detect MET amplification (MET/CEP7 ratio > 2.0 and GCN > 4.0) showing the difficulty of establishing a correlation between protein overexpression and its ability to detect MET amplification." (PMID 37046637, 2023). "This suggested that cMET signaling may not be critical in patients with gastric cancer without MET amplification." (PMID 37046637, 2023). "In addition, the high expression of MET and CLDN9 may potentially predict the prognosis of gastric cancer patients, whereas the role of TKTL1 remains unclear." (PMID 37980488, 2023). "Three receptor tyrosine kinases (RTKs), MET, ErbB2, and FGFR2, have been widely studied in gastric cancer (GC)." (PMID 35884507, 2022). "A combination of MET and HER2 targeted therapies exerted a significant synergism in gastric cancer PDX models, suggesting this combination strategy may be a potential therapeutic option for some gastric cancer patients and warrants a further investigation in clinical studies." (PMID 34557411, 2021). "Therefore, the MET/AKT/mTOR axis may be an important target for Cy to inhibit the growth and migration of gastric cancer cells." (PMID 34830011, 2021). "Indeed, joint overexpression of DRs and their ligand often promotes aggressive tumor progression, as was, for example, shown for HGF and c‐MET in NSCLC or gastric cancer, suggestive of a positive selection for ligand‐induced rather than ligand‐independent signaling." (PMID 34542930, 2021). "However, PI3K-AKT signaling does not seem to play a crucial role in the present context, since PI3K inhibition in gastric cancer cells had no impact on basal HER3 expression or on HER3 induction after MET inhibitor treatment." (PMID 33374770, 2020). "Thus, both the phosphorylated and non-phosphorylated forms of CagA can interact with MET and stimulate downstream signaling pathways in gastric cancer progression." (PMID 33217986, 2020). "However, the effect was not obvious in gastric cancer cells with moderate MET and AXL expression SNU719 cells." (PMID 34766112, 2020). "The fact that Akt phosphorylation after MET inhibition is more efficiently restored by HRG treatment of gastric cancer cells than by EGF treatment is in line with previous findings and indicates that PI3K-Akt signaling is of particular importance for survival signaling in gastric cancer cells." (PMID 33374770, 2020). "The TCGA dataset was used to explore the landscape of MET, PD-1 ligand, and T-cell effector molecule expression in human cancers, specifically, the potential biological and clinical relevance of MET and PD-L1 in the tumor immune microenvironment of NSCLC and gastric cancer." (PMID 31480591, 2019). "Therefore, in the present study, the anti-cancer effects of the c-MET inhibitor on gastric cancer cells from positive or negative for c-MET amplification were evaluated." (PMID 30871613, 2019). "Furthermore, we observed that afatinib treatment decreased the proliferation in NCI‐N87, MKN1, and MKN7 cells but not in Hs746T cells, suggesting that MET amplification is a potential resistance factor in gastric cancer." (PMID 29325228, 2018). "MET is highly amplified in MKN45 gastric cancer cells, but with no MET exon 14 skipping." (PMID 29188469, 2018). "Furthermore, induction of apoptosis by ABT-700 was seen in other cell lines with amplified MET including SNU620 gastric cancer and EBC1 NSCLC but not in Hs746T and MKN45 gastric cancer cells (data not shown)." (PMID 26879245, 2016).
gastric cancer (continued). "Although rilotumumab (an anti-HGF antibody) and onartuzumab (an anti-MET antibody) have not been found to confer survival benefit in non-small cell lung or gastric cancers, rilotumumab reportedly showed survival benefit when used with panitumumab in a phase II trial." (PMID 27296289, 2016). "Receptor tyrosine kinase (RTK)-related genes, including HER2, EGFR, MET, FGFR2 and KRAS, are target molecules that are clinically beneficial in gastric cancer (GC)." (PMID 27014419, 2016). "Similarly, onartuzumab, a monovalent anti-c-MET antibody, also failed to deliver clinical benefits when it was combined with mFOLFOX6 as the first-line treatment in patients with advanced gastric cancer." (PMID 27581465, 2016). "Additionally, METex14del has been reported in gastric cancer (GC) cell line Hs746T and neuroblastoma indicating this is a potential common mechanism for a variety of tumors to delay the ubiquitination and down-regulation of MET protein leading to its overexpression." (PMID 26375439, 2015). "Therefore, we used additional ten (five each amplified and non-amplified) gastric cancer samples and MET amplified gastric cancer cell lines (MKN45 and SNU5) with known copy numbers and mRNA amounts." (PMID 25372287, 2014). "Because of the fact that an optimal threshold has not been defined, the cut-off defining a gastric cancer with MET expression and gene amplification is arbitrary, which might produce bias." (PMID 24416238, 2014). "Furthermore some gastric cancers harbour DNA amplification or overexpression of the RTK MET and its paralogue MST1R and may be treated with MET or MST1R inhibitors." (PMID 21781349, 2011). "For instance, approximately 5% of patients with gastric cancer (GC) have increased copy numbers (no. of gene copies >4) of the MET gene." (PMID 36483096, 2022). "In our study, volitinib combined with trastuzumab had a significant synergism in three gastric cancer PDX models compared to volitinib or trastuzumab alone, which was not evident in NCI-N87 cell with HER2 high expression and MET low expression." (PMID 34557411, 2021). "Agents inhibiting hepatocyte growth factor receptor (c-MET) signaling, such as the anti-MET antibody onartuzumab or the small molecular inhibitor tivantinib, have been evaluated in gastric cancer without achieving sufficient clinical benefits." (PMID 28852882, 2018). "There are several known non-ERBB regulators of ERBB3, such as MET, BRK, EBP-1 and CDK5, in gastric cancer." (PMID 26942872, 2016). "The IM95 gastric cancer cell line was included for comparative analysis since it exhibits autocrine HGF signaling and dependence on c-Met signaling in the absence of MET amplification." (PMID 26879245, 2016). "c-MET, HGF, and HGF-c-MET complexes in FFPE specimens of human Non-Small Cell Lung Cancer (NSCLC), Gastric Cancer, Head and Neck Squamous Cell, and Head and Neck Non-Squamous Cell carcinomas." (PMID 21283737, 2011). "Notably, in the gastric cancer cells investigated here, SATB1 knockdown had no impact on the basal expression of any HER receptor; however, the upregulation of HER3 upon MET inhibition was prevented." (PMID 33374770, 2020). "MET (Mesenchymal-Epithelial Transition) oncogene, also called Hepatocyte Growth Factor Receptor (HGF), is a receptor tyrosine kinase that appears to be deregulated in many human cancers, such as breast, colorectal, lung, pancreatic, hepatic and—not least—gastric cancer." (PMID 30205505, 2018). "In the absence of MET amplification, MET has been found to be overexpressed in a variety of cancers, such as RCC, NSCLC, malignant pleural mesothelioma (MPM), glioblastoma multiforme (GBM), and gastric cancer (GC)." (PMID 38675409, 2024).
non-small cell lung carcinoma (384 papers, 2004 to 2026). A group of at least three distinct histological types of lung cancer, including non-small cell squamous cell carcinoma, adenocarcinoma, and large cell carcinoma. "Non-small cell lung cancer (NSCLC) harboring MET exon 14 skipping mutations or MET overexpression/amplification typically exhibits highly proliferative and invasive phenotypes and is a significant threat to human health." (PMID 41368576, 2025). "One of the most common MET oncogenic mutations, occurring in approximately 5% of non-small cell lung cancer, falls outside of the KD and results in skipping of exon 14, which encodes the N-terminal half of the MET intracellular juxtamembrane (JM) domain." (PMID 41383124, 2025). "MET exon 14 skipping mutations have emerged as significant driver alterations in non-small-cell lung cancer (NSCLC), contributing to tumor progression." (PMID 40710213, 2025). "MET mutations have become a significant mechanism of resistance to ALK inhibitors in ALK-rearranged non-small-cell lung cancer." (PMID 40422509, 2025). "Tepotinib is widely utilized for treating non-small cell lung cancer (NSCLC) patients with MET exon 14 (METex14) skipping mutations." (PMID 41411333, 2025). "MET exon 14 (METex14) skipping variants occur in 0.6–4% of non-small cell lung cancer (NSCLC), adenocarcinomas, and belong to the group of molecular biomarkers whose testing is recommended in international guidelines." (PMID 41515986, 2025). "For non-small cell lung cancers (NSCLCs), capmatinib, tepotinib, and crizotinib are currently recommended for patients with high-level MET amplification or MET exon 14 skipping mutations in the US." (PMID 38892160, 2024). "Capmatinib is a tyrosine kinase inhibitor against c-MET, recently approved for the treatment of metastatic non-small cell lung cancer with MET mutations." (PMID 38339363, 2024). "In the VISION trial enrolling 152 non-small cell lung cancer patients, tepotinib afforded an overall response rate of 46% in patients with MET exon-14 skipping mutations." (PMID 38339049, 2024). "MET exon 14 skipping is one of the rare mutations in non-small cell lung cancer (NSCLC), involving its pathogenesis and progression." (PMID 37400762, 2023). "In 2021, FDA accelerated the approval of Tepotinib for marketing to treat adult patients with metastatic non-small cell lung cancer with MET exon 14 (MET ex14) jump mutation." (PMID 37945598, 2023). "In this narrative review, we discuss the development of capmatinib, a reversible MET tyrosine kinase inhibitor that received approval for advanced non-small cell lung cancer (NSCLC) harboring MET exon 14 skipping mutation." (PMID 37509224, 2023). "Patients with non-small-cell lung cancer suffered from MET gene mutations, and treatment of capmatinib inhibited tumor activity in the patients with MET mutations." (PMID 35685832, 2022). "Two type Ib MET-tyrosine kinase inhibitors (TKIs), capmatinib and tepotinib, were recently approved for the treatment of non-small-cell lung cancer (NSCLC) patients carrying MET exon 14 skipping mutations (METex14)." (PMID 35690785, 2022). "MET exon 14 skipping mutation (METex14) is observed in ~3% of non-small cell lung cancer (NSCLC) cases and has been shown to be an independent poor prognostic factor associated with shorter overall disease-specific survival." (PMID 35280795, 2022). "Capmatinib and tepotinib are guideline-recommended front-line treatments for non-small-cell lung cancer (NSCLC) patients with MET exon 14 skipping mutations (METex14)." (PMID 35690785, 2022). "MET amplification and its most relevant somatic splice-site mutation that results in a skipping of exon 14 are both potential predictive biomarkers for non-small-cell lung cancer (NSCLC)." (PMID 35069735, 2022). "The targeted agents capmatinib and tepotinib provide a new treatment for patients with non-small cell lung cancer (NSCLC) with MET exon 14 skipping mutation (METex14)." (PMID 36233109, 2022).